GRIK5 (glutamate ionotropic receptor kainate type subunit 5)
Description:
Ionotropic glutamate receptor that functions as a cation-permeable ligand-gated ion channel, gated by L-glutamate and the glutamatergic agonist kainic acid. Cannot form functional channels on its own and produces channel activity only in heteromeric assembly with GRIK1 and GRIK2 subunits. Can form functional heteromeric receptors with GRIK3 (By similarity).
Synonyms: GluK5; EAA2; KA2; GRIK2
Tractability: Small molecule: an approved drug acts on it; a high-quality ligand is known; it belongs to a druggable protein family. Antibody: UniProt places it where antibodies can reach, with high confidence; its Gene Ontology location is reachable by antibodies, with high confidence; UniProt predicts a signal peptide or a membrane-spanning region; the Human Protein Atlas places it where antibodies can reach. PROTAC: its protein half-life has been measured; a small molecule that binds it is known.
Target class: Ionotropic glutamate receptor; Kainate receptor; Ligand-gated ion channel; Ion channel
Chemical probes: Iodo-Willardiine
Gene: Protein-coding gene on chromosome 19 (41,998,316 to 42,070,240, reverse strand). Ensembl gene ENSG00000105737.
Subcellular location: Cell membrane; Postsynaptic cell membrane; Presynaptic cell membrane
Subcellular location (Human Protein Atlas): Plasma membrane; Nucleoplasm
Pathways (Reactome):
Neuronal System: Activation of Ca-permeable Kainate Receptor
Gene Ontology:
Molecular function: glutamate-gated receptor activity; kainate selective glutamate receptor activity; ligand-gated monoatomic ion channel activity involved in regulation of presynaptic membrane potential; transmitter-gated monoatomic ion channel activity involved in regulation of postsynaptic membrane potential; ligand-gated monoatomic ion channel activity; monoatomic ion channel activity; signaling receptor activity
Biological process: glutamate receptor signaling pathway; modulation of chemical synaptic transmission; synaptic transmission, glutamatergic; ionotropic glutamate receptor signaling pathway; monoatomic ion transmembrane transport; monoatomic ion transport; regulation of postsynaptic membrane potential; regulation of presynaptic membrane potential; signal transduction
Cellular component: plasma membrane; glutamatergic synapse; kainate selective glutamate receptor complex; postsynaptic density membrane; postsynaptic membrane; presynaptic membrane; endoplasmic reticulum; hippocampal mossy fiber to CA3 synapse; membrane
Genetic constraint (gnomAD): Loss-of-function variants: 40 observed, 88.01 expected, observed/expected ratio (o/e) 0.45, 90% interval 0.35 to 0.59. The upper end of that interval is the gene's LOEUF score, 0.59, which puts it in group 2 of 6, group 1 being the genes least tolerant of losing a copy. Missense variants: 951 observed, 1,260.2 expected, observed/expected ratio (o/e) 0.75, 90% interval 0.71 to 0.8. Synonymous variants: 545 observed, 524.79 expected, observed/expected ratio (o/e) 1.04, 90% interval 0.97 to 1.12.
Homologues: Orthologues: chimpanzee GRIK5 (99% identical), macaque GRIK5 (99% identical), dog GRIK5 (99% identical), pig GRIK5 (99% identical), mouse Grik5 (99% identical), rat Grik5 (99% identical), guinea pig GRIK5 (86% identical), rabbit GRIK5 (83% identical), tropical clawed frog grik5 (82% identical), zebrafish grik5 (80% identical), Drosophila melanogaster CG11155 (35% identical), Drosophila melanogaster Ekar (32% identical), and 39 more. Paralogues in human: GRIK4 (67% identical), GRIK2 (41% identical), GRIK3 (39% identical), GRIK1 (39% identical), GRIA3 (32% identical), GRIA1 (31% identical), GRIA2 (31% identical), GRIA4 (31% identical), GRID1 (24% identical), GRID2 (23% identical), GRIN1 (23% identical), GRIN2A (20% identical), and 5 more.
Diseases named in the same sentence as GRIK5 in open-access papers:
GRIK5 is named in the same sentence as 23 diseases in open-access papers, as found by Europe PMC text mining. Sharing a sentence is not in itself a finding about the gene and the disease. The quoted sentences say what the papers report.
schizophrenia (6 papers, 2013 to 2022). A major psychotic disorder characterized by abnormalities in the perception or expression of reality. "Therefore, we sequenced the exonic regions of five kainate receptor genes (GRIK1, GRIK2, GRIK3, GRIK4, and GRIK5) to identify rare pathogenic variants in patients with schizophrenia using the ion semiconductor sequencing method." (PMID 35629206, 2022). "After resequencing 516 unrelated patients with schizophrenia, 44 protein-altering variants were identified, including 12 in the GRIK1, 5 in the GRIK2, 7 in the GRIK3, 13 in the GRIK4, and 7 in the GRIK5." (PMID 35629206, 2022). "In addition, A895G located within the cytoplasmic protein domain of GRIK5, was found protective at a nominal level of significance against developing schizophrenia (p = 4.06 × 10−5; OR = 44.83, CI 2.70–765)." (PMID 31844109, 2019).
autism (2 papers, 2019 to 2025). Persistent deficits in social interaction and communication and interaction as well as a markedly restricted repertoire of activity and interest as well as repetitive patterns of behavior. "The GRIK gene family (GRIK1, GRIK2, GRIK3, GRIK4, and GRIK5) has genetic variants associated with many psychiatric illnesses including; depression, obsessive–compulsive disorder, and autism." (PMID 41327126, 2025). "The GRIK gene family (GRIK1, GRIK2, GRIK3, GRIK4, and GRIK5) has genetic variants that contribute to various illnesses, including Huntington's disease, Parkinson's disease, autism, and schizophrenia." (PMID 41327126, 2025).
melanoma (2 papers, 2022 to 2023). A malignant, usually aggressive tumor composed of atypical, neoplastic melanocytes. "Furthermore, GRIK5 has been identified as a potential biomarker for melanoma metastatic progression." (PMID 38099288, 2023).
anxiety disorder (1 paper, 2022). A category of psychiatric disorders which are characterized by anxious feelings or fear often accompanied by physical symptoms associated with anxiety. "The authors identified strong associations to individual disorders, such as GHRH with anxiety disorders, PREB with eating disorders, and GRIK5 with bipolar disorder." (PMID 35893041, 2022).
breast carcinoma (1 paper, 2022). "Expression of metastatic state ion channels GRIK5 (p-value: 0.51) and CLCNKB (p-value: 0.18) were also associated with survival in breast cancer patients." (PMID 35326596, 2022).
colorectal cancer (1 paper, 2023). A primary or metastatic malignant neoplasm that affects the colon or rectum. "Although limited research exists on the relationship between GRIK5 expression and colorectal cancer (CRC), our study fills this gap by identifying a significant association between high GRIK5 expression and CRC progression." (PMID 38099288, 2023).
metastatic melanoma (1 paper, 2022). A melanoma that has spread from its primary site to another anatomic site. "Interestingly, the Glutamate Ionotropic Receptor Kainate Type Subunit 5 (GRIK5) identified here for the first time as a classifier for primary vs. metastatic melanoma, is mainly known for its role in neural development and neuropsychiatric disorders." (PMID 36553569, 2022). "In the SKCM data set, the expression of GRIK5 does not seem to be significantly different between primary and metastatic melanoma." (PMID 36553569, 2022).
migraines (1 paper, 2021). "Topiramate is an FDA-approved GRIK5 inhibitor employed as an antiepileptic drug and is used to manage seizures and prevent migraines." (PMID 34872356, 2021).
nematode infection (1 paper, 2019). "Two sub-units of NMDARS, NR2A and NR2B (also known as Grin2A and Grin2B) as well as several AMPARs including the metabotropic glutamate receptors 1 and 2 (mGlu-R1 and mGlu-R2), Gria3, Grm2, Grm4, Grik3 and Grik5 were up-regulated in the pup brain on P7 in response to maternal nematode infection." (PMID 30862816, 2019).
psychosis (1 paper, 2019). "For the psychosis grouping, we observed a genome-wide significant burden of rare LoF and missense variants within GRIK5 (p = 7.83 × 10−10) and an increased burden of common and rare functional variants within NETO1 (p = 6.76 × 10−6)." (PMID 31844109, 2019).
cancer (4 papers, 2014 to 2024). A tumor composed of atypical neoplastic, often pleomorphic cells that invade other tissues. "Most of the current research on Grik5 is related to the proliferation and metastasis of cancer cells." (PMID 39056737, 2024). "The expression of CHRNA3, GABRD, GRIK3, and GRIK5 in cancer cells significantly impacted their response to chemotherapy." (PMID 38099288, 2023). "Our analysis of drug sensitivity revealed that the expression of CHRNA3, GABRD, GRIK3, and GRIK5 in cancer cells significantly impacted their response to chemotherapy." (PMID 38099288, 2023). "Furthermore, the contribution of GNRH2, PRLH, GPR156, GRIK5, LHB, and CRHR2 to the neuroactive ligand-receptor interaction pathway are specified in ATLL in consistent with some other cancers." (PMID 34446027, 2021).
neurological disorders (1 paper, 2023). "GRIK5 is another excitatory glutamate receptor for which reduced expression has been associated with eye and vascular disease, and whose variants have been associated with neurological disorders." (PMID 37968596, 2023).
tumor (1 paper, 2023). "The CHRNA3, GABRD, GRIK3 and GRIK5 gene are associated with the sensitivity of certain anti-tumor drugs such as fluphenazine, pimozide, isotretinoin, and fludarabine." (PMID 38099288, 2023). "Results revealed that, compared to normal tissues, the expression of CHRNA3, GRIK3, and GRIK5 is decreased in tumor tissues, while GABRD is highly expressed in tumor tissues, consistent with our bioinformatics analysis results." (PMID 38099288, 2023).
GRIK5 also shares sentences with these, for which no sentence is quoted: epilepsy (4 papers); depression (2); alcoholics (1); atherosclerosis (1); bipolar disorder (1); cardiac arrhythmia (1); eating disorder (1); mental disorder (1); mood disorder (1); neuropathy (1).